PGD (phosphogluconate dehydrogenase)
Description:
Catalyzes the oxidative decarboxylation of 6-phosphogluconate to ribulose 5-phosphate and CO(2), with concomitant reduction of NADP to NADPH.
Synonyms: 6PGD
Tractability: Small molecule: a structure with a bound ligand is known; it has a high-quality binding pocket; it belongs to a druggable protein family. PROTAC: ubiquitination databases record sites on it; its protein half-life has been measured; a small molecule that binds it is known.
Target class: Enzyme; Oxidoreductase
Gene: Protein-coding gene on chromosome 1 (10,398,592 to 10,420,511, forward strand). Ensembl gene ENSG00000142657.
Subcellular location: Cytoplasm
Subcellular location (Human Protein Atlas): Cytosol; Mitochondria; Nucleoplasm; Plasma membrane
Pathways (Reactome):
Cellular responses to stimuli: NFE2L2 regulates pentose phosphate pathway genes
Metabolism: Pentose phosphate pathway
Gene Ontology:
Molecular function: phosphogluconate dehydrogenase (decarboxylating) activity; NADP binding; carbohydrate binding; carboxylic acid binding
Biological process: pentose-phosphate shunt, oxidative branch; pentose-phosphate shunt; D-gluconate metabolic process; NADP+ metabolic process; NADPH regeneration
Cellular component: extracellular exosome; nucleus; cytosol; cytoplasm
Genetic constraint (gnomAD): Loss-of-function variants: 16 observed, 44.06 expected, observed/expected ratio (o/e) 0.36, 90% interval 0.25 to 0.55. The upper end of that interval is the gene's LOEUF score, 0.55, which puts it in group 2 of 6, group 1 being the genes least tolerant of losing a copy. Missense variants: 385 observed, 517.2 expected, observed/expected ratio (o/e) 0.74, 90% interval 0.68 to 0.81. Synonymous variants: 191 observed, 203.94 expected, observed/expected ratio (o/e) 0.94, 90% interval 0.83 to 1.06.
Homologues: Orthologues: chimpanzee PGD (99% identical), macaque PGD (99% identical), dog PGD (95% identical), pig PGD (94% identical), mouse Pgd (94% identical), rabbit PGD (93% identical), rat Pgd (93% identical), zebrafish pgd (88% identical), Drosophila melanogaster Pgd (72% identical), Caenorhabditis elegans T25B9.9 (70% identical), guinea pig PGD (56% identical).
Diseases named in the same sentence as PGD in open-access papers:
PGD is named in the same sentence as 52 diseases in open-access papers, as found by Europe PMC text mining. Sharing a sentence is not in itself a finding about the gene and the disease. The quoted sentences say what the papers report.
lung carcinoma (14 papers, 2017 to 2025). "For instance, YTHDF2 interacts with the 3’-untranslated region (UTR) of 6-phosphogluconate dehydrogenase (6PGD) to enhance mRNA translation, thereby promoting lung cancer cell proliferation." (PMID 39138186, 2024). "Knockdown of 6‐phosphogluconate dehydrogenase (PGD) of the PPP has been shown to inhibit the growth of lung cancer cells by inducing cell senescence, which was thought to occur through accumulation of growth‐inhibitory glucose metabolics." (PMID 30108113, 2018). "Further analysis on ALDH2, ALDH3a1, FBP1, PGD, TALDO1, and TPI1 as biomarkers on the evolution of IPF patients, their association with PJ infection, and their lung cancer risk could be relevant." (PMID 39997396, 2025). "Moreover, ovarian and lung cancer patients with higher PGD levels have worse survival outcomes relative to patients with lower PGD expression." (PMID 34645978, 2021). "In addition, YTHDF2 was found to be upregulated in lung cancer tissues, to promote cell growth in lung cancer, and to bind directly to the m6A-modified site in the 6-phosphogluconate dehydrogenase (6PGD) 3′ UTR." (PMID 32398132, 2020). "Expression of PPP enzymes such as G6P dehydrogenase (G6PD), 6-phosphogluconate dehydrogenase (PGD), and transketolase (TKT) was directly regulated by NRF2 in lung cancer cells, and NRF2 overexpression redirected cell metabolism to PPP-mediated purine nucleotide synthesis." (PMID 31078780, 2019).
breast carcinoma (7 papers, 2018 to 2026). "Higher PGD expression correlated with worse distant relapse-free survival in the entire breast cancer cohort and in a subset of TNBC patients." (PMID 41535266, 2026). "PGD upregulation has been proved to be related to the occurrence and development of a variety of tumors, including breast cancer, colon cancer, cervical cancer, and so on, and this may be due to the coordinated regulation of PGD involved in anabolic and redox." (PMID 36338768, 2022). "Similarly, we found out that 6-phosphogluconate dehydrogenase (6PGD), the third enzyme of ox-PPP, also has significant importance in the proliferation of breast cancer cells." (PMID 34572981, 2021).
colon cancer (3 papers, 2018 to 2025). "Furthermore, five of the seven glycolytic and PPP enzymes identified in our interactome analysis (GOT2, GPI, PGD, PSAT1, and TKT) were found to map to the “Metabolic reprogramming in colon cancer” pathway." (PMID 30108113, 2018).
neuroblastoma (3 papers, 2004 to 2025). Neuroblastoma (NB) is the most common solid, extracranial childhood tumor. "As a control, we included the neuroblastoma cell line NB-1, which is defective in glycolysis due to the loss of phosphogluconate dehydrogenase." (PMID 39809754, 2025). "A gene was predicted to reside distal to the CORT gene but proximal to the PGD gene, in the neuroblastoma tumour suppressor gene candidate region on chromosome 1p36.22." (PMID 15328517, 2004). "Similarly, PT also exerted significant growth inhibition against 2 independent human cancer xenograft models having different metabolic backgrounds (melanoma, A2058 with complete glycolytic activity; neuroblastoma, NB-1 with deletion of a glycolytic enzyme, PGD)." (PMID 34623325, 2021).
non-small cell lung carcinoma (3 papers, 2017 to 2020). A group of at least three distinct histological types of lung cancer, including non-small cell squamous cell carcinoma, adenocarcinoma, and large cell carcinoma. "In terms of energy metabolism, G6PD and PGD, associated with the pentose phosphate pathway, can prevent erastin-induced ferroptosis when it is knocked down in non-small cell lung cancer cells." (PMID 33330074, 2020).
thyroid cancer (3 papers, 2020 to 2025). "Meanwhile, AKR1C1, HMGCR, TFRC, SQLE, and PGD were risk factors for thyroid cancer prognosis." (PMID 33928101, 2021). "Our data suggested that AKR1C1 (p < 0.0001), DPP4 (p < 0.0001), GPX4 (p = 0.0001), GSS (p < 0.0001), HMGCR (p < 0.0001), TFRC (p < 0.0001), SQLE (p = 0.0004), and PGD (p = 0.0005) were all significantly highly expressed in thyroid cancer tissues compared to normal tissues." (PMID 33928101, 2021). "By using CaMeRe, the corresponding reaction with the PGD involved could also be identified in multiple cancers, such as Bladder Urothelial carcinoma (BLCA), Breast invasive carcinoma (BRCA) and Thyroid carcinoma (THCA)." (PMID 32161720, 2020).
cervical cancer (2 papers, 2020 to 2022). A primary or metastatic malignant neoplasm involving the cervix. "Previous studies have reported the up-regulation of PGD in kinds of human cancers, such as cervical cancer, ovarian cancer, lung cancer, and so on." (PMID 36338768, 2022). "Recent work suggested that 6-phosphogluconate dehydrogenase (6PGD), the key enzyme of oxidative pentose phosphate pathway (PPP), could act as a potential therapeutic target to enhance chemosensitivity in cervical cancer." (PMID 32327612, 2020).
COVID-19 (2 papers, 2020 to 2021). A disease caused by infection with severe acute respiratory syndrome coronavirus 2. "In module 2, mono-CD14+ cells in patients with severe COVID-19 exhibited higher expression levels of glycolysis-related genes (LDHA and PKM) and PPP-related genes (PGD and TKT), which may be involved in the proinflammatory response (upregulation of S100A8, S100A9, S100A12, and IL1B)." (PMID 33936072, 2021).
diabetes (2 papers, 2023). "This increase in PGD activity points towards an adaptive response to the heightened oxidative stress commonly associated with diabetes." (PMID 38203517, 2023). "For instance, TXNDC5’s interactions with NENF, PPP1R2, ALDOC, LDH, or PGD may help explain its relevance in diabetes." (PMID 38138960, 2023).
fatty liver (2 papers, 2024 to 2025). "Furthermore, based on network pharmacology predictions, molecular docking studies suggested that the primary targets of Catechin gallate in alleviating fatty liver might include ABCB1, DYRK1A, PGD, and FUT4." (PMID 40699724, 2025).
fatty liver disease (2 papers, 2024 to 2025). A reversible condition wherein large vacuoles of triglyceride fat accumulate in liver cells via the process of steatosis. "In this study, through network pharmacology and molecular docking, we identified potential targets for Catechin gallate in the treatment of fatty liver disease, which include ABCB1, DYRK1A, PGD, and FUT4." (PMID 40699724, 2025).
lung adenocarcinoma (2 papers, 2017 to 2021). A carcinoma that arises from the lung and is characterized by the presence of malignant glandular epithelial cells. "NRF2-regulated PPP genes, including G6PD, PGD, TKT, and TALDO1 were first identified in lung adenocarcinoma A549 cells." (PMID 33859744, 2021).
psoriasis (2 papers, 2023 to 2024). An autoimmune condition characterized by red, well-delineated plaques with silvery scales that are usually on the extensor surfaces and scalp. "Then, 5 potential hub genes (SOD2, PGD, PPIF, GYS1, AHCY) of psoriasis were identified by protein–protein interaction (PPI) networks using Metascape database." (PMID 36890558, 2023). "Together, the 5 hub genes (SOD2, PGD, PPIF, GYS1 and AHCY) play pivotal roles in the development of psoriasis." (PMID 36890558, 2023). "We found that SOD2, PGD, PPIF, GYS1 and AHCY are five hub genes in PPI networks, indicating the potential role in the psoriasis initiation and progression." (PMID 36890558, 2023). "Five potential hub genes of psoriasis were obtained, including SOD2, PGD, PPIF, GYS1 and AHCY." (PMID 36890558, 2023). "However, the potential role of PGD, PPIF, GYS1 and AHCY has not been explored in psoriasis." (PMID 36890558, 2023).
schizophrenia (2 papers, 2021 to 2025). A major psychotic disorder characterized by abnormalities in the perception or expression of reality. "Previous studies have suggested that 6-phosphogluconate dehydrogenase (PGD) expression is interrupted due to microRNA expression in schizophrenia and bipolar disorder and fluctuates during frontotemporal lobar degeneration (FTLD)." (PMID 40102990, 2025). "Adjunctive aripiprazole, metformin, and PGD showed beneficial effects in reducing AP-induced hyperprolactinemia in schizophrenia, with aripiprazole (<5 mg/day) being the most effective one." (PMID 34658963, 2021).
Sepsis (2 papers, 2021 to 2025). Sepsis is defined as life-threatening organ dysfunction caused by a dysregulated host response to infection. "Notably, the expression patterns of core PCD-related genes in this cohort were highly consistent with those observed in the discovery datasets, with genes such as CYBB, GCLM, MAP1LC3B, NCKAP1, and PGD markedly upregulated in sepsis patients." (PMID 41346577, 2025).
Cirrhosis (1 paper, 2018). A chronic disorder of the liver in which liver tissue becomes scarred and is partially replaced by regenerative nodules and fibrotic tissue resulting in loss of liver function. "For the oxidative phase of PPP enzymes, high G6PD mRNA expression levels were found to be associated with a progression of cirrhosis to HCC and reduced survival rate (P = 0.0209), while PGLS and PGD show no differential expression (P > 0.050)." (PMID 30430110, 2018).
gastrointestinal stromal tumor (1 paper, 2020). "One of the rate-limiting enzymes of the PPP-phosphogluconate dehydrogenase (PGD), is dramatically upregulated in gastrointestinal stromal tumors (GISTs) and GIST cell lines resistant to Imatinib (IM) compared with sensitive controls." (PMID 32719331, 2020).
glioma (1 paper, 2021). A benign or malignant brain and spinal cord tumor that arises from glial cells (astrocytes, oligodendrocytes, ependymal cells). "Thus, we developed a prognostic prediction model for glioma patients using four mRNAs, namely, SNCG, PGD, CDK6, and GCC1." (PMID 34615480, 2021).
hereditary leiomyomatosis (1 paper, 2020). "Moreover, treatment of OXPHOS-competent hereditary leiomyomatosis RCC with the complex I inhibitor IACS-010759 plus simultaneous inhibition of the glycolytic enzyme phosphogluconate dehydrogenase (PGD) led to synthetic lethality." (PMID 33092283, 2020).
influenza (1 paper, 2018). An acute viral infection of the respiratory tract, occurring in isolated cases, in epidemics, or in pandemics; it is caused by serologically different strains of viruses (influenzaviruses) designated A, B, and C, has a 3-day incubation period, and usually lasts for 3 to 10 days. "Despite previous findings that the gene PGD is essential for influenza replication, knockdown of PGD did not result in any suppression of influenza WSN replication in our hands in A549 or NHBE cells." (PMID 29775471, 2018).
myocardial infarction (1 paper, 2022). Gross necrosis of the myocardium, as a result of interruption of the blood supply to the area, as in coronary thrombosis. "The differences in ATG7 expression and PGD expression did not occur until more than 48 h after myocardial infarction." (PMID 36407421, 2022).
pancreatic cancer (1 paper, 2020). "Distant metastases from pancreatic cancer patients were previously reported by the authors to be dependent on the glucose-metabolizing enzyme phosphogluconate dehydrogenase (PGD)." (PMID 32792504, 2020).
promyelocytic leukaemia (1 paper, 2016). "Interestingly, depletion of enzymes in oxidative PPP, i.e. G6PD, PGLS (6-phosphogluconolactonase), and PGD, dramatically abrogated the proliferation of HL-60, a human promyelocytic leukaemia cell line." (PMID 27586085, 2016).
renal cell carcinoma (1 paper, 2022). "Additionally, PGD activation increased the chemo- and immune-resistance of renal cell carcinoma (RCC) cells, and PGD inhibition made RCC cells sensitive to chemotherapy and immunotherapy (such as IFN-α)." (PMID 36338768, 2022).
rheumatoid arthritis (1 paper, 2023). A chronic, systemic autoimmune disorder characterized by inflammation in the synovial membranes and articular surfaces. "For example, salivary PGD level was altered in patients with rheumatoid arthritis compared to healthy subjects." (PMID 37723556, 2023).
Stroke (1 paper, 2024). Sudden impairment of blood flow to a part of the brain due to occlusion or rupture of an artery to the brain. "Altered PGD expression can influence stroke outcomes by affecting the cell’s oxidative stress response." (PMID 39595569, 2024).
T cell deficiency (1 paper, 2025). "We showed that donor T cell deficiency in 6-phosphogluconate dehydrogenase (6PGD), the second rate-limiting enzyme in the PPP, significantly reduced aGvHD severity and mortality in murine models." (PMID 41355795, 2025).
cancer (35 papers, 2012 to 2025). A tumor composed of atypical neoplastic, often pleomorphic cells that invade other tissues. "PGD has been reported to overexpress in a number of cancer types and to be associated with poor prognosis." (PMID 34819946, 2021). "PGD is one of the key enzymes in cancer reprogramming, and the loss-of-function of PGD will cause a significant effect on the reprogrammed epigenetic state, malignant gene expression and anabolic glucose metabolism." (PMID 32161720, 2020). "Enzymes from the PPP, like glucose 6-phosphate dehydrogenase (G6PD) and 6-phosphogluconate dehydrogenase (6PGD), are essential for fulfilling the energy and biosynthetic requirements of cancer cells." (PMID 40142097, 2025). "6‐phosphogluconate dehydrogenase (6PGD) activity, an important enzyme for cancer pathogenesis and tumor development, was increased in many cancers." (PMID 38213102, 2024). "Targeting 6-phosphogluconate dehydrogenase (6PGD) can inhibit cancer cell proliferation and tumor growth." (PMID 33817181, 2019). "These genes were significantly downregulated in most cancer cell lines except for gene PGD." (PMID 37007025, 2023). "Decreasing PGD phosphorylation through EGFR signaling could dramatically attenuate cancer cells’ proliferation, growth and resistance to ionizing radiation." (PMID 34906147, 2021). "In addition, the upregulated expression of PGD also performs a key role in the development of radiochemotherapeutic resistance in cancer." (PMID 34819946, 2021). "Total proteomics analysis revealed a significant increase in the abundance of two key enzymes in the oxidative branch of pentose phosphate pathway (PPP), glucose-6-phosphate dehydrogenase (G6PD) and 6-phosphogluconate dehydrogenase (6PGD) in cancer cells exposed to FAK-depleted CAF CM." (PMID 32157087, 2020). "Hence, in addition to their known anti-cancer roles, our findings suggest the therapeutic response of tumors to inhibitors of PGD and G6PD will be amplified at acidic pHi." (PMID 30065243, 2018). "Besides, many previous studies have demonstrated that overexpression of PGD could lead to cancer metastasis and poor prognosis." (PMID 34434214, 2021). "As an example, consistent with studies in cancer cells, we found that Nrf2 significantly boosted several genes in the pentose phosphate pathway, including those for glucose-6-phosphate dehydrogenase (G6pd), transaldolase 1 (Taldo1), and phosphogluconate dehydrogenase (Pgd)." (PMID 33491671, 2021). "6-phosphogluconate dehydrogenase (6PGD) is a key metabolic enzyme in the pentose phosphate pathway (PPP), which displays aberrant expressions and functions in cancer." (PMID 40611205, 2025). "By knocking down these four candidate transcriptional factors using siRNA in cultured ccRCC cancer cells, we found the mRNA levels of G6PD and PGD decreased in SP1 knocking down cells." (PMID 37460463, 2023). "The G6PD, PGD, TKT, and TALDO1 support glucose flux and generate purines, which are building blocks of DNA and RNA, which help to accelerate proliferation in cancer cells." (PMID 33922165, 2021). "Other identified targets in our analysis, notably PGD and G6PD from the pentose phosphate pathway, are also predicted to have both anti-proliferative and anti-Warburg effects on cancer." (PMID 30065243, 2018). "6-phosphogluconate dehydrogenase (6PGD) is the third enzyme in the oxidative PPP, and is important for cancer cell growth." (PMID 28713273, 2017). "Lastly, it is also noteworthy that two enzymes of the non-oxidative branch of the PPP were found less oxidized in cancer, and protein levels of 6-phosphogluconate dehydrogenase (6PGD) were increased." (PMID 40461450, 2025). "NRF2 plays a crucial role in promoting the proliferation of cancer cells and metabolism process in lung cancer cells, including the direct transcriptional regulation of PPP-related enzymes such as G6PD, PGD, TKT, and TALDO1, which are responsible for NADPH regeneration." (PMID 33922165, 2021).
cancer (continued). "uncovered that PGD could act as a regulator in the process of CD8+ T cell activation and differentiation, suggesting that PGD might serve as a key therapeutic target for cancer immunotherapy." (PMID 36338768, 2022).